FANCD2 (FA complementation group D2)
Diseases named in the same sentence as FANCD2 in open-access papers (continued):
Sharing a sentence is not in itself a finding about the gene and the disease.
cancer (continued). "Interestingly, ASPM was found in EV derived from serum, urine, and different types of cancer cells; FANCD2 in EV of serum, urine and CRC cells; and PIWIL4 (a canonical RBP) was also found in serum, urine and CRC cells." (PMID 38903178, 2024). "Secondly, even though our study has demonstrated a correlation between FANCD2 expression and immune activity as well as clinical survival in pan-cancer, we cannot definitively confirm whether FANCD2 directly impacts clinical survival through an immune pathway." (PMID 38443946, 2024). "In addition to its proficiency in repairing DNA damage, FANCD2 also assumes pivotal roles in the progression of cancer." (PMID 38443946, 2024). "The analysis demonstrated that, in general, FANCD2 could exhibit adverse effects on overall survival, disease-specific survival, or progression-free intervals in some cancer cases." (PMID 38443946, 2024). "FANCD2 expression was positively correlated with the G2/M pathway in 33 pan-carcinomas." (PMID 38443946, 2024). "Similarly, our integrated analysis identified CDKN1A and FANCD2 as the key genes of STARD14 playing a cancer promoting role in LUAD." (PMID 37790851, 2023). "FANCD2 is a ferroptosis suppressor involved in DNA repair and has been studied in other cancers." (PMID 37821996, 2023). "Finally combined with survival analysis identified CDKN1A and FANCD2 as the key genes of STARD14 playing a cancer promoting role in LUAD." (PMID 37790851, 2023). "Thus, FANCD2 has the potential to become an attractive target for understanding and treating cancer." (PMID 37821996, 2023). "Meanwhile, ferroptosis related gene (FANCD2) may be potential therapeutic targets for a variety of cancers." (PMID 36276091, 2022). "Owing to numerous pathways that FANCD2 could regulate in the occurrence and development of cancer, it deserves deeper investigation." (PMID 35646059, 2022). "We further evaluated whether FANCD2 expression is high in most human cancers compared with matched normal samples utilizing the starBase database." (PMID 36246623, 2022). "And FANCD2 was markedly correlated with the prognosis of the most human cancer." (PMID 36276091, 2022). "We found the interaction between ZNF419 and FANCD2 might involve in ferroptosis in pan-cancer level." (PMID 36578929, 2022). "Therefore, as a regulator of FANCM, FANCD2 will be an excellent target candidate for the treatment of ALT cancers." (PMID 34743173, 2021). "Because the unique nuclear protein complex that ubiquitinates FANCD2 and FANCI leads to formation of DNA repair structures, it is postulated that they may affect cancer risk in a specific manner." (PMID 34549727, 2021). "FANCD2, a nuclear protein that responds to DNA damage repair, negatively regulated ferroptosis of bone marrow injury in cancer treatment and could be a potential target of anticancer therapies." (PMID 34820377, 2021). "POLQ expression in different cancer types strongly correlated with the expression of factors involved in response to replicative stress (RAD51, FANCD2, and BLM), instead of genes encoding for several core MMEJ proteins, factors involved in DNA end resection or in canonical NHEJ." (PMID 34201502, 2021). "Therefore, small molecule-mediated inhibition of the proteins required for the regulated ubiquitination and deubiquitination of FANCD2/FANCI represents a promising strategy to induce cancer-specific killing." (PMID 32409752, 2020). "Therefore, inhibition of FANCD2 mono-ubiquitination represents a possible therapeutic strategy for cancer specific killing." (PMID 32409752, 2020). "This could be related to differences in the functions of FANCD2 in mESCs compared to human cancer cells." (PMID 33200984, 2020). "We found a frameshift mutation in RAD51C and deleterious mutations, one splicing and one frameshift, in two FANC members not previously associated with cancer risk, FANCD2 and FANCI, respectively." (PMID 29659569, 2018).
cancer (continued). "Therefore, we emphasize the importance of the V2/V1 ratio to more accurately describe the relationship between FANCD2 with cancer and aging." (PMID 28157704, 2017). "Therefore, both the N-terminal domain (AA42-72) of ATP5α and the monoubiquitination of FANCD2 at K561 play critical roles in cellular energy metabolism, enhancing our understanding of aging and cancer in general." (PMID 28687786, 2017). "The FANCD2 foci formation may be assayed to predict the sensitivity of cancer cells to cisplatin and PARPi, given that PARP inhibitors, chemotherapy and radiotherapy induce FANCD2 nuclear foci formation." (PMID 27884198, 2016). "Nine percent of the Bi-L E7/K14–tTA/FancD2+/+ mice developed cancer." (PMID 27190216, 2016). "We also observed that FA deficiency marginally increased the disease severity (for Bi-L E7/K14–tTA/FancD2+/+ versus Bi-L E7/K14-tTA/FancD2−/−, P = 0.11) while greatly increasing the incidence of cancers (for Bi-L E7/K14–tTA/FancD2+/+ versus Bi-L E7/K14-tTA/FancD2−/−, P = 0.0026)." (PMID 27190216, 2016). "Severity of disease and cancer incidence in the cervix are independent of continued expression of HPV16 E7 on the FancD2-deficient background but not on the FancD2-sufficient background." (PMID 27190216, 2016). "In the future it would be very interesting to screen different human cancers for additional WDR48 mutations that might not only be defective in maintaining PHLPP1 function but also other substrates such as BRCA1, FANCD2, H2A/H2B, PCNA, and notch receptor." (PMID 24145035, 2013). "Moreover, we have identified a 189 bp DNA fragment downstream of the ΔNp63 promoter (P2) that can mediate the upregulation of ΔNp63 by an inactivated FANCD2, and determined that elevated ΔNp63 is high enough to promote cancer cell proliferation and metastasis." (PMID 23965832, 2013). "However, the comprehensive understanding of FANCD2’s role in various cancer types remains limited." (PMID 38443946, 2024). "Therefore, we analyzed the expression correlation of FANCD2 and four MMR genes and identified that the expression of FANCD2 and these four MMR genes had a significant positive correlation, indicating that higher expression of FANCD2 correlated with lower response rates of cancer immunotherapy LUAD." (PMID 36267413, 2022). "Additionally, FANCD2 expression could serve as an indicator of response rates to cancer immunotherapy." (PMID 36267413, 2022). "Moreover, targeting ferroptosis (FANCD2) could be a potential therapeutic alternative for various cancers." (PMID 36276091, 2022). "The FA D2 group protein (FANCD2) and its paralog form the focal point of FA signaling to converge the effects of its upstream players in response to a variety of cellular insults and simultaneously with downstream players to protect humans from contracting diseases, including aging and cancer." (PMID 34884777, 2021). "mTOR signaling may promote the survival of cancer cells via enhancing the expression of FANCD2, CHK1 and RRM2 through CDK4/6 while inhibiting ATM, revealing the potential mechanisms of the increased cancer cell growth and proliferation under stressful conditions." (PMID 31285446, 2019). "As a first step in testing this hypothesis, we carried out a pilot study to analyze the expression of five proteins (Ki-67, Cyclin E, POLD3, γH2AX and FANCD2) on a collection of 32 tumor samples from a representative range of cancer types (colon, lung, breast or stomach)." (PMID 28445142, 2017).
cancer (continued). "In contrast, the difference in the overall severities of disease when E7 was turned off in the FancD2-sufficient background was highly significant (for Bi-L E7/K14–tTA/FancD2+/+ versus Bi-L E7/K14–tTA/FancD2+/+ [Dox], P = 2.644 × 10−6; P = 7.9 × 10−6 if we exclude cancers)." (PMID 27190216, 2016). "However, we observed that E7-driven cancers in FancD2-deficient mice become independent of continued expression of E7." (PMID 27190216, 2016). "Additionally, the IL-6- and/or MYC-driven mouse models of human BL and MM used in this study may lend themselves to the biological validation of CDKN1A and FANCD2 as molecular targets for new approaches to cancer therapy and prevention." (PMID 25838973, 2015). "This indicates that the tumorigenicity of compromised FANCD2 activation is, at least partly, attributed to inactivated FANCD2-triggerred ΔNp63 expression, and thus provides a novel insight into the development of an effective tool for genetically intervening in cancer cell growth." (PMID 23965832, 2013). "Among the 38 scrutinized subsets of immune cells, we observed a direct correlation between FANCD2 expression and the degree of Th2 CD4 + T-cell infiltration across 32 diverse cancer types." (PMID 38443946, 2024). "We observed that the protein levels of FANCD2, RAD51, and ATR, which promote alternative end-joining, DNA damage repair, and cancer cell survival, were downregulated." (PMID 37020276, 2023). "Seeing as FANCI has a similar function to FANCD2 in the DDR pathway and is closely related, it is necessary to investigate the role of FANCI in cancer." (PMID 37324186, 2023). "The effect of the FA pathway, especially the FANCD2-FANCI heterodimer, is twofold in cancer progression." (PMID 37324186, 2023). "Then, we further performed a pan-cancer analysis of AKR1C3 and FANCD2 across different human cancers by Wilcox test." (PMID 36276091, 2022). "Finally, FANCD2 expression was confirmed to be positively related to HCC immune cell infiltration, immune checkpoints, and IPS analysis, and GSEA results also revealed that this ferroptosis-associated gene was primarily involved in cancer-associated pathways in HCC." (PMID 36246623, 2022). "Besides, FANCD2 could be a potential prognostic biomarker in different cancer types." (PMID 36276091, 2022). "In our study, we analyzed 14 genes that are significantly related to some or most anticancer drugs, such as FANCD2, HSPA5, NFE2L2, ACSL4, and DPP4 in the Cancer Therapeutic Response Portal Database." (PMID 35309947, 2022). "Among the interface genes in the Her2+_TNBC module, the known cancer-related genes are mostly DNA repair genes, such as BARD1, BRIP1, BRCA1, BRCA2, FANCA, FANCC, FANCD2, and FEN1." (PMID 35992864, 2022). "The results demonstrated that the higher expression level of FANCD2 correlated with a higher TIDE score, indicating lower response rates to cancer immunotherapy." (PMID 36267413, 2022). "Hence, ZNF419 may regulate ferroptosis through FANCD2 at the pan-cancer level." (PMID 36578929, 2022). "Further studies on FANCD2 in LUAD will provide a new perspective on the correlation of FANCD2 with TIME and diverse strategies for cancer immunotherapy." (PMID 36267413, 2022). "We further explored the effect of 5 hub genes (ACSL4, FANCD2, HIF3A, HSPA5, and PSMB7) in 33 kinds of cancer in the TCGA database." (PMID 35652069, 2022). "We have also discussed potential biomarkers involved in pathways that are differentially affected or modified during the onset of HPV-related cancers, such as Akt, mTOR, miRNAs, TNF-α, TGF-β, BRCA1, and FANCD2." (PMID 33668730, 2021). "USP1 function as an oncogene by interacting with DNA repair signal through PCNA and FANCD2, USP4 promote cancer progression by deubiquitinating TRAF2 and TRAF6 and thereby regulating the TGFβ signaling pathway." (PMID 34545063, 2021).
cancer (continued). "It is noteworthy that the ferroptosis suppressor genes, SLC3A2, FANCD2, CISD1, and ACSL3, were upregulated in most cancer types, indicating that ferroptosis was generally inhibited in cancers." (PMID 34434214, 2021). "Our study lays the foundation for more comprehensive experimental study (in vitro, in vivo) on modulating the cell death drug targets FANCD2, NCOA4 (COAD), IKBKB, (GBM), and RHOA (GBM and SCLC), to improve the therapeutic avenues in cancer treatment." (PMID 33670487, 2021). "Combined, these suggest that FANCD2 and FANCI regulate the further molecular machineries for chromatin-based processes and many others, preventing the human genome from going awry for cancer and other human diseases." (PMID 34884777, 2021). "Here, we show that Doxorubicin hydrochloride (D-HCL) targets FANCD2 in COAD, and interestingly, Doxorubicin induces cell death in cancer cells." (PMID 33670487, 2021). "Consistent with the results from the cancer cell lines, targeting BRIP1 as well as several other components of the FA pathway, such as FANCD2 and FANCI, significantly impaired the fitness of ALDH2 KO cells as compared to the WT." (PMID 34454516, 2021). "However, future overexpression experiments in normal esophageal epithelial cell lines are needed to clarify whether the malignant phenotype of FANCD2 overexpression is only present in transformed cells and, therefore, reflects a late step in cancer evolution of ESCC." (PMID 32906798, 2020). "In Bi-L E7/K14-tTA/FancD2−/− mice, we likewise observed expression of MCM7 throughout the epithelial cells within the cancers and the cervical epithelium." (PMID 27190216, 2016). "We performed Western immunoblot analysis to evaluate the expression level of PAR, FancD2, and ERCC1, in the human cancer cell lines H1299 following exposure to veliparib." (PMID 25566506, 2014). "Regulation of DNA repair genes (FANCD2 and RNR) suggests that the PI3K-AKT-mTOR signaling promotes cancer cell survival and resistance to radiation treatment by enhancing the DNA damage repair of the cancer cells." (PMID 25988165, 2014). "Previously published data suggest that FANCD2 and FANCJ knockdown in HNSCC cell lines enhances aggressive cancer phenotypes, such as epithelial-to-mesenchymal (EMT)-like morphological changes and increased invasion, at least in part due to metabolic dysregulation." (PMID 40805278, 2025). "Specifically, we compared FANCD2 genome binding in our three datasets to existing MiDAS datasets for two cancer-derived cell lines (HeLa and U2OS) and one non-cancer-derived line (HS68)." (PMID 39365306, 2024). "The two types of cancer cell lines used in this study are shown to respond differently to CIT exposure, and additionally, differences in the intensity of changes in (phospho)Chk2 and (phospho)FANCD2 were also observed." (PMID 39057961, 2024). "However, in some cancers such as PAAD, FANCD2 expression is consistent throughout disease progression." (PMID 38443946, 2024). "Moreover, MEF2D binding activity to FANCD2, EXO1, and XRCC4 was significantly higher in cancer cells than in normal cells, and ARN3261 significantly reduced MEF2D binding activity to FANCD2, EXO1, and XRCC4 in cancer cells compared with normal cells." (PMID 35642638, 2022). "Of these, seven genes (BRIP1, ERCC4, FANCD2, FANCG, FANCI, MAD2L2, PPP2R2A) were previously related to the platinum sensitivity/resistance of different types of cancer cells, with NPEPPS being reported for the first time as a platinum drug sensitivity regulator." (PMID 35209078, 2022). "Almost all the FRGs in signaling pathways of pan-cancer, STMN1, RRM2, HELLS, FANCD2, and AURKA could significantly activate the cell cycle, but inhibit EMT, DNA damage response, hormones ER, RAS/MAPK, and RTK." (PMID 36349201, 2022). "Furthermore, the differential expression of FANCD2 between GBM and its corresponding non-cancer tissues can be confirmed by GEPIA." (PMID 35754466, 2022).
cancer (continued). "In addition, higher FANCD2 expression was related to a higher tumor immune dysfunction and exclusion (TIDE) score, indicating lower responder rates to cancer immunotherapeutics." (PMID 36267413, 2022). "When FANCI or FANCD2 is not properly functioning, both can lead eventually not only to cancer as emphasized herein but also to aging and many other states, including metabolic disorders." (PMID 34884777, 2021). "Indeed, induction of antioxidant gene expression by FANCD2 and FOXO3 can also impact on cancer therapy resistance as radiotherapy and chemotherapeutic drugs can influence cancer treatment outcome through their modulation of ROS." (PMID 32372224, 2020). "Why are the roles of FANCD2 and FANCI in cancer predisposition not identified, though they are central participants in the FA pathway?" (PMID 32300589, 2020). "We found monoallelic functionally deleterious mutations in three genes of the FA family, namely RAD51C (FANCO), FANCD2 and FANCI genes, the latter two not previously associated with cancer risk." (PMID 29659569, 2018). "Previous publications have shown that the degree of immunohistochemical staining of carcinoma cells for the proteins described, OPN, S100A4, S100P, AGR2 and FANCD2, reflect the level of each particular protein in the specimens." (PMID 27100728, 2016). "Nevertheless, there are many different FANCJ mutations that have been identified in FA patients as well as in different cancers and it is possible that some of these may alter FANCJ and FANCD2 interactions." (PMID 26336824, 2015). "Ubiquitination of FANCD2 and PCNA is important for their roles in DNA repair, suggesting that subversion of USP1 in human cancers might impinge on transformation events through alterations of DNA repair pathways." (PMID 21283576, 2011). "Importantly, normal immortalized foreskin keratinocytes (NIKS) and normal oral keratinocytes (NOKS) did not harbor increased total protein levels upon FANCD2 knockdown, indicating that the observed increase is a cancer-specific response." (PMID 40805278, 2025). "Importantly, co-depleting FANCD2 together with SETX impairs cancer cell proliferation, without significantly affecting non-cancerous cells." (PMID 36543851, 2022). "Taken together, SIK2 inhibition decreases PARP enzyme activity and the expression of FANCD2, EXO1, and XRCC4, suggesting that the combination of a SIK2 inhibitor and PARP inhibitor has the potential to increase the magnitude and duration of PARP inhibitor activity in patients with different cancers." (PMID 35642638, 2022). "Survival analysis further revealed that only FANCD2 at a high expression level had shorter OS and DFS survival in HCC, indicating that this gene could serve as a potential and prognostic target in this deadly cancer." (PMID 36246623, 2022). "Likewise, mice deficient in key FA pathway proteins, including Fancc, Fancg, Fanca, and Fancd2, also do not develop cancers until later in life (14 months of age), and only Fancc-/- mice are known to develop AML/MDS in old age." (PMID 34804941, 2021). "A search for predicted nonsynonymous mutations in a set of 138 genes that are known to be mutated by single-base substitutions and indels in human cancers yielded heterozygous single-base substitutions in RET and FANCD2 that were not present in either of the two normal genomes that we sequenced." (PMID 22341448, 2012). "However, a comprehensive pan-cancer analysis of FANCD2 has been lacking." (PMID 38443946, 2024). "The expression levels of FANCD2, TP53BP1, and RPA2 were statistically significantly elevated in HGD and in carcinomas, according to the results of non-parametric Friedman tests." (PMID 36061145, 2022).
cancer (continued). "Currently, the expression of FANCD2 did not increase by MMC treatment because MMC repressed DNA replication by inhibiting DNA replication and transcription to eliminate cancer cells." (PMID 32486251, 2020). "However, in Bi-L E7/K14-tTA/FancD2−/− mice treated with doxycycline, expression of MCM7 was restricted in its expression to the poorly differentiated cells not only within the epithelium but also in the cancers, confirming that E7 is no longer expressed in those cancers." (PMID 27190216, 2016).